KRAS (KRas proto-oncogene, GTPase)
Diseases named in the same sentence as KRAS in open-access papers (continued):
Sharing a sentence is not in itself a finding about the gene and the disease.
colorectal cancer (continued). "Here, by leveraging the largest synthetic lethal genetic interactome in yeast, we identify that KRAS‐mutated colorectal cancer cells have augmented homologous recombination repair (HRR) signaling." (PMID 28173629, 2017). "PNB-qPCR was successfully applied in a study, detecting KRAS mutated tumour DNA in colorectal cancer patients during respective tumour surgery." (PMID 28827745, 2017). "The mechanisms most commonly proposed for colorectal cancer recurrence, besides tumor stage, location, and cancer treatment, include KRAS and mismatch repair gene mutations, microsatellite instability status, and MCMT promoter methylation." (PMID 28620703, 2017). "The clinical significance of KRAS codon 13 mutation in patients with colorectal cancer (CRC) remains controversial." (PMID 28858102, 2017). "We determined the prognostic value of BRAF and KRAS mutations in Korean colorectal cancer (CRC) patients." (PMID 28583095, 2017). "The majority of colorectal cancer cells (53%) show mutation on KRAS, being characterized by the activation of both mitogen activated protein kinase (MAPK) and phosphoinositide 3-kinase (PI3K) signaling pathways." (PMID 29185464, 2017). "Activating KRAS mutations drive colorectal cancer tumorigenesis and influence response to anti‐EGFR‐targeted therapy." (PMID 28173629, 2017). "High levels of nuclear RAD21 staining correlate with poor disease-specific survival of colorectal cancer patients with KRAS mutations and with early relapse in patients with high-grade luminal, basal, or HER2 breast cancers." (PMID 28434945, 2017). "In contrast to colorectal cancers, activating mutations in KRAS are a rare event in gastric cancer, present in approximately 5% of tumors." (PMID 29237412, 2017). "A mutation was defined as informative when it contributed to the understanding of the clinical course, such as association with disease aggressiveness or selection against certain therapies (e.g. KRAS mutations in colorectal cancer)." (PMID 28423702, 2017). "The clearest example is the predictive value of pre-therapeutic screening of KRAS mutations in patients with colorectal cancer prior to cetuximab therapy, an approach allowing individually-tailored therapeutic strategies." (PMID 28532501, 2017). "Upon further evaluation, she was found to have colorectal cancer positive for KRAS and BRAF mutations." (PMID 28811946, 2017). "Among the numerous genetic alterations which have been connected to resistance to cetuximab, activating mutations in the KRAS gene are especially important in colorectal cancer regimens." (PMID 27933395, 2017). "Low EZH2 expression was significantly associated with a shorter PFS and OS in patients with KRAS (codon 12/13) wild-type group colorectal cancer treated with anti-EGFR therapeutics." (PMID 28147317, 2017). "Currently, the most clinically significant mutated genes in colorectal cancer are KRAS, NRAS and BRAF as these genes provide information on a patients’ prognosis and their suitability for anti-EGFR therapies." (PMID 29029407, 2017). "KRAS mutation is one of the most frequent molecular abnormalities found in several types of cancer such as pancreatic cancer, colorectal cancer, non-small cell lung cancer." (PMID 28796802, 2017). "We have recently reported that KRAS mutations in colorectal cancer (CRC) cause alterations in amino acid metabolism." (PMID 28749408, 2017). "In fact, the KRAS mutation has been reported to be present in 50% of colorectal cancers and is often mono-allelic, suggesting the presence of mutated and non-mutated KRAS proteins in the same cells." (PMID 28933766, 2017).
colorectal cancer (continued). "This is of special interest because KRAS amplifications in colorectal cancers were shown to be associated with resistance to EGFR inhibitors, including cetuximab." (PMID 29237412, 2017). "Approximately 40–45% of colorectal cancers harbor KRAS mutations, and mutation status is predictive of resistance to anti‐EGFR‐based targeted therapy in patients with metastatic colorectal cancer receiving cetuximab or panitumumab." (PMID 28173629, 2017). "In colorectal cancer, activating mutations in the KRAS gene were shown to be associated with therapeutic failure of cetuximab-containing regimens." (PMID 27933395, 2017). "In a corollary finding, Cetuximab therapy in colorectal cancer patients based on a KRAS mutational profile has been quite promising." (PMID 29068423, 2017). "PLCD1 has also been identified as a TSG in gastric cancer, oesophageal squamous cell carcinoma, KRAS-mutated colorectal cancer, chronic myeloid leukaemia, and breast cancer in our previous work." (PMID 28423710, 2017). "KRAS mutations in primary tumor samples and metastasis in colorectal cancer have been described as highly similar with a concordance of 93–97%37,38." (PMID 28674438, 2017). "Our current study showed a significant correlation between EZH2 expression and KRAS (codon 61/146) mutation in colorectal cancers." (PMID 28147317, 2017). "High miR-31-3p expression is associated with inferior outcomes in KRAS wild-type (WT) advanced colorectal cancer patients treated with anti-EGFR therapy." (PMID 29212194, 2017). "KRAS mutation status is crucial for treatment of colorectal cancer patients, as anti-EGFR therapy is ineffective in the presence of KRAS mutations." (PMID 28827745, 2017). "Generally, the prevalence of KRAS mutations in tumor tissues was high than that of cfDNA in pancreatic cancer and colorectal cancer." (PMID 28796802, 2017). "We uncovered an overall KRAS mutation rate of 36.7% in colorectal cancers, which was consistent with most previous reports." (PMID 28583095, 2017). "Treatment of patients with colorectal cancer whose tumors bear a KRAS mutation remains a therapeutic challenge to this day." (PMID 28422714, 2017). "While extensive data is available on the predictive and prognostic significance of KRAS mutation in colorectal carcinoma (CRC), we have ambiguous information on its prognostic role in lung cancer." (PMID 28051122, 2017). "Colorectal cancer patients had 35.62 copies of mutated KRAS per milliliter of plasma (median), whereas in healthy controls only residual copies were found (0.62 copies/mL, p = 0.0066)." (PMID 27043547, 2016). "We found that 28.9% of the 495 colorectal cancer precursor lesions had mutations in the KRAS gene which was in range with the 15.0%-75.0% prevalence of KRAS mutations in polyps reported in previous studies." (PMID 26910894, 2016). "We found striking similarities between colorectal cancers and adenomas during the evaluation of KRAS and BRAF mutations." (PMID 26910894, 2016). "This is significant because KRAS mutations mediate resistance to cetuximab and approximately 50% of colorectal cancer patients display this mutation." (PMID 27150056, 2016). "Specifically, we target the heterozygous G13A activating mutation of KRAS in colorectal cancer cells and we show reversal of drug resistance to a MEK small-molecule inhibitor." (PMID 26788852, 2016). "To date, most of the blood samples used in KRAS mutation tests have been obtained from colorectal cancer (CRC) patients." (PMID 27519791, 2016). "Ly6H mRNA expression was significantly increased in colorectal cancer with KRAS mutation (n=27) than KRAS wildtype tumors (n=43) in Khambata-Ford study." (PMID 26862846, 2016). "Activating mutations in KRAS are common in colorectal cancer but have also been reported in 5–16% of gastric and esophageal adenocarcinomas, causing unregulated signalling along its pathway, independently of EGFR status." (PMID 26844548, 2016).
colorectal cancer (continued). "Activating mutations of KRAS (KRASmut) are among the most prevalent oncogenic mutations in human cancers and occur in approximately half of human colorectal cancer." (PMID 26744320, 2016). "KRAS G12V mutation circulating in plasma was detected in 9 of 10 colorectal cancer patients whose tumors were also mutated." (PMID 27043547, 2016). "Here, the results of a multi-center study testing archived FFPE tumor samples from colorectal cancer patients for their KRAS mutational status with the IdyllaTM KRAS Mutation Assay (RUO) are reported." (PMID 27685259, 2016). "Seventy-five of the patients presented potential actionable mutations, whereas an additional 26 patients with colorectal cancer had KRAS wild type status." (PMID 26968814, 2016). "The KRAS gene is mutated in about 40 % of colorectal cancer (CRC) cases, which has been clinically validated as a predictive mutational marker of intrinsic resistance to anti-EGFR inhibitor (EGFRi) therapy." (PMID 27756306, 2016). "Mechanisms or reasons for exclusive hot spot mutations were similar to KRAS/BRAF exclusive mutations in colorectal cancer." (PMID 26848617, 2016). "It has been shown that human colorectal cancer cells carrying KRAS and BRAF mutations—giving them a highly glycolytic phenotype—can be selectively killed by high doses of vitamin C." (PMID 27616976, 2016). "Colorectal cancer patients, particularly those with KRAS mutations, are still awaiting successful alternative targeted therapies to be implemented in clinical practice." (PMID 27602501, 2016). "We found that individuals over the age of 60 years had about a 1.3-fold increase in risk of having a KRAS mutant colorectal cancer precursor lesion than younger individuals in a univariate analysis." (PMID 26910894, 2016). "The success rate of colorectal cancer clinical trials has remained low as patients—in particular those with KRAS mutations—have shown resistance to a broad palate of targeted therapies." (PMID 27897178, 2016). "In KRAS mutated colorectal cancer cells, which are resistant to anti-EGFR therapy, combining of terpinen-4-ol with cetuximab (1 μM) resulted in impressive efficacy of 80–90% growth inhibition." (PMID 27275783, 2016). "Mutated KRAS is reported in approximately 35%-45% of colorectal cancers and >90% of pancreatic ductal adenocarcinoma (PDAC)." (PMID 27323830, 2016). "KRAS G12V mutation was detected in all colorectal cancer patients tested, with the exception of one." (PMID 27043547, 2016). "In our current study, the frequency of KRAS mutations was 34.8%, consistent with most reports from other populations, suggesting that such an alternation exists in 30-40% of colorectal cancer." (PMID 27050078, 2016). "In order to evaluate our primer system we used human colorectal cancer cell lines harboring distinct genomic KRAS mutations." (PMID 27064574, 2016). "In this study, KRAS G12V mutation was analyzed by ddPCR in plasma DNA from 10 colorectal cancer patients and compared to six healthy donors." (PMID 27043547, 2016). "Activating KRAS mutation (KRASmut) is the most prevalent oncogenic driver in colorectal cancer development, and KRASmut inhibition represents an unmet clinical need." (PMID 26744320, 2016). "The KRAS gene mutations have been found above in 40 % of colorectal cancers and in 15–25 % of non-small cell lung cancer (NSCLC)—predominantly in patients with adenocarcinoma and smoking history." (PMID 25902737, 2016). "Oncogenic KRas mutations induce CSC of colorectal cancer cells carrying an Apc mutation, as shown by comparisons of sphere formation, transforming potential, chemoresistance and expression of stem cell markers." (PMID 27655692, 2016). "Anti-EGFR targeted therapy is of increasing importance in advanced colorectal cancer and prior KRAS mutation testing is mandatory for therapy." (PMID 27064574, 2016).
colorectal cancer (continued). "Our data show that p62, LC3 and Beclin-1 represent promising novel therapeutic targets especially in the subgroup of KRAS-mutated colorectal cancer patients." (PMID 27444698, 2016). "In the present study, we observed that the frequency of KRAS oncogene mutations in codons 12 and 13 in 270 samples of colorectal cancer Thai patients was 44.44%." (PMID 26812617, 2016). "The KRAS oncogene is mutated in approximately 35–45 % of colorectal cancers and KRAS mutations are considered to be more predominant in pancreatic, thyroid, colorectal, and lung cancers." (PMID 27535739, 2016). "Additional evidence for these rare subclones has been provided by the detection of low levels of KRAS mutations by sensitive PCR technology in patients with colorectal cancer who were found to be wild type for KRAS by standard methods." (PMID 26912072, 2016). "Colorectal cancer patients had 35.62 copies of mutated KRAS/mL plasma, whereas in healthy controls only residual copies were found (0.62 copies/mL, p = 0.0066)." (PMID 27043547, 2016). "The MAS-PCR assay provides a rapid, cost-effective, and reliable diagnostic tool for accurate detection of KRAS mutations in routine FFPE colorectal cancer tissues." (PMID 26812617, 2016). "KRAS mutations are responsible for resistance to anti-epidermal growth factor receptor (EGFR) therapy in colorectal cancer patients." (PMID 27043547, 2016). "It is now well established that the frequency of detected KRAS mutations in colorectal cancer is influenced by the analytical sensitivity of the method applied for their detection." (PMID 27685259, 2016). "We observed that colorectal cancer patients had mutated KRAS circulating in plasma as well as elevated levels of wild-type KRAS in comparison to healthy controls (p = 0.0066 and p = 0.0002, respectively)." (PMID 27043547, 2016). "Using the IdyllaTM KRAS Mutation Assay, the KRAS mutational status of 374 archived clinical colorectal cancer FFPE samples was tested at 12 centers." (PMID 27685259, 2016). "KRAS (Kirsten rat sarcoma viral oncogene homolog) mutation is a common oncogenic driver observed in different solid cancers like colorectal cancer, pancreatic cancer, and lung cancer." (PMID 27433281, 2016). "For example, KRAS point mutations in codon 12 or 13 occur in 35–50% of colorectal cancers and in 80–90% of pancreatic cancers." (PMID 26999437, 2016). "Most prevalent in colorectal cancer are KRAS exon 2 mutations (40% prevalence); lower prevalence is observed for KRAS exon 3 and 4 mutations (6%) and NRAS exon 2, 3, and 4 mutations (5%)." (PMID 27685259, 2016). "Combination of HRM and pyrosequencing in a two-step diagnostic procedure constitutes a reliable and economic analysis platform for KRAS mutation testing in colorectal cancer in a clinical setting." (PMID 27485514, 2016). "In this study, 4302 patients with at least one colorectal polyp from a large colorectal cancer screening program were evaluated and genetic mutations in either KRAS or BRAF were detected in 495 patients." (PMID 26910894, 2016). "This particular mutation occurred in 43.4% of the colorectal cancer precursor lesions with KRAS mutations." (PMID 26910894, 2016). "The metabolic inhibitor 3-bromopyruvate (3-BrPA) is a promising anti-cancer alkylating agent, shown to inhibit growth of some colorectal carcinoma with KRAS mutation." (PMID 27863474, 2016). "3-BrPA preferentially suppressed the growth of some colorectal carcinoma cells with KRAS or BRAF mutations which survived glucose starvation." (PMID 27863474, 2016). "We developed a multiplex allele specific assay specific based in screen the 7 most common KRAS mutations in codons 12 and 13 for colorectal carcinoma, using an allele specific qPCR assay." (PMID 27632281, 2016). "3-BrPA at 110 μM was shown to suppress the growth of colorectal carcinoma cells with KRAS or BRAF mutations surviving glucose starvation." (PMID 27863474, 2016).
colorectal cancer (continued). "We focussed our study on colorectal carcinoma cell lines, because approximately 50% of colorectal tumors contain a mutated KRAS gene, and further 10% harbor mutated BRAF." (PMID 26799289, 2016). "We used medical subject headings, including colorectal cancer, molecular genetics, KRAS and BRAF mutations, screening, survival, epidemiologic study, and Iran." (PMID 25685149, 2015). "Double mutations in KRAS in colorectal cancer have been reported before, however their clinical relevance is not known." (PMID 25568935, 2015). "The frequency of KRAS mutations is 34.6% in colorectal cancer, according to the COSMIC (Catalogue of Somatic Mutation in Cancer) database." (PMID 25674493, 2015). "Mutations in codon 12 and 13 of the KRAS gene are found in ~30% of colorectal cancer (CRC) cases and are associated with an increased risk of recurrence and mortality." (PMID 25823645, 2015). "The use of an isogenic panel of colorectal cancer cells differing only in the presence of a heterozygous KRAS mutation allowed the presence and influence of the most frequently observed tumour-associated variants to be characterised." (PMID 26560143, 2015). "One study analyzing colorectal cancer EV contents found mutant KRAS protein was present in EVs isolated from DKO-1 cells with KRAS mutation." (PMID 26231887, 2015). "Our results show that castPCR is a reproducible and reliable assay that can be used as a diagnostic test for KRAS genotyping in formalin-fixed paraffin-embedded colorectal cancer samples." (PMID 25568935, 2015). "For example, KRAS mutations are known to block the effect of therapeutic EGFR inhibition by antibodies or small inhibitors in colorectal cancer patients." (PMID 25398926, 2015). "In view of the role of RALA in RAS-induced tumorigenesis in human cells and particularly its involvement in colorectal cancer, we investigated the role of RALA in colorectal cancer cell lines carrying KRAS mutations in codon 12, 13 or the BRAF V600E mutation." (PMID 26033452, 2015). "This is in line with our observations that colorectal cancers from patients with a history of current or former smoking were less likely to harbor a KRAS mutation." (PMID 26530529, 2015). "The RALA pathway is robustly active in colorectal cancer cell lines harboring KRAS or BRAF driver mutations." (PMID 26033452, 2015). "The Sanger sequencing method is currently the gold standard, however, several KRAS mutation kits have become available for colorectal cancer patients." (PMID 25674493, 2015). "It is also limited to higher incidence biomarker subgroups (KRAS mutation ∼40% of colorectal cancers) such that there is adequate statistical power to identify a differential benefit based on the biomarker." (PMID 25557400, 2015). "Apart from this fact, we and others have reported that KRAS mutation in colorectal cancer itself is associated with pulmonary metastasis." (PMID 25888291, 2015). "Vemurafenib, a BRAF inhibitor, reduced pS-EphA2 in cells harbouring BRAF mutation, but rather increased pS-EphA2 in NRAS-mutated SK-MEL-2 cells as well as in KRAS-mutated DLD-1 human colorectal cancer cells." (PMID 26158630, 2015). "Our previous study in colorectal cancer cell lines revealed that the KRAS G12D mutation decreased the impact of CIP2A on downstream effectors of the EGFR signaling pathway, when cells were treated with temsirolimus." (PMID 25896895, 2015). "Mutations in this gene play the equivalent role that KRAS mutations play in chromosomal instability colorectal cancer." (PMID 25977829, 2015).